EGFR (epidermal growth factor receptor)
Diseases named in the same sentence as EGFR in open-access papers (continued):
Sharing a sentence is not in itself a finding about the gene and the disease.
lung cancer (continued). "Therefore, the use of epidermal growth factor receptor tyrosine kinase inhibitor (EGFR‐TKI) is one of the research hotspots in lung cancer treatment." (PMID 38054663, 2023). "In this study, we used an in vivo mouse model of lung cancer i.e., EGFRL858R mice, in which lung cancer is induced by doxycycline treatment, to establish an animal model of drug resistance by long-term treatment with 20 mg/kg gefitinib, an EGFR tyrosine kinase inhibitor (TKI)." (PMID 36918558, 2023). "At the European Lung Cancer Congress (ELCC) in 2022, Hu Jian's research proved for the first time that almonertinib had significant efficacy and good safety as postoperative adjuvant treatment of stage I-III NSCLC with EGFR mutation." (PMID 36890493, 2023). "Recent studies have shown that the EGFR signaling component may participate in the induction of COX-2 levels in lung cancer cell lines." (PMID 37893002, 2023). "Our results suggest that the 218-5p/EGFR signaling pathway may be a potential therapeutic target for the treatment of lung cancer induced by chronic arsenic exposure." (PMID 36831545, 2023). "Our results showed that NF1 mutations had no direct effect on OS in LUAD cases or LUSC cases, even in lung cancer patients without driver genes (EGFR mutations and ALK fusion)." (PMID 35702826, 2023). "Moreover, Axl confers resistance to EGFR-targeted therapy in lung cancer by interacting with ErbB3 and phosphorylation of Akt." (PMID 37746265, 2023). "In addition, EGFR-activated AKT is associated with cytomembrane PD-L1 expression and survival in patients with lung cancer." (PMID 37554324, 2023). "Surprisingly, the combination of 8PN and EGFR TKIs induced apoptosis, as indicated by cleavage of caspase 3, revealing that the combination treatment could trigger programmed cell death in lung cancer cells." (PMID 37013960, 2023). "The identification of epidermal growth factor receptor (EGFR) gene mutations and the therapeutic efficacy of EGFR tyrosine kinase inhibitors (EGFR-TKIs) in this subgroup of tumors established the basis for biomarker-driven lung cancer therapy." (PMID 37798663, 2023). "In addition, numerous lung-cancer-related mutations (e.g., in ALK, EGFR, and pmKRAS) as well as the loss of heterozygosity, microsatellite instability, and gene methylation, are also readily detected in these cfDNA." (PMID 37371825, 2023). "EGFR mutant lung cancer incidence values were compared with mean PM2.5 values across geographical regions using Pearson correlation tests, weighted Pearson correlation tests (to account for number of tested cases in each geographical region) and robust linear regression (to account for outliers)." (PMID 37020004, 2023). "Both studies suggest that EGFR has an important role in the mechanism of lung cancer development." (PMID 36787056, 2023). "In this study, we showed that the expression of CNOT3 could be regulated by EGFR signaling in lung cancer." (PMID 37919290, 2023). "Functionally, both colony formation and transwell assays supported that overexpression of NEDD4L inhibited the proliferation and metastasis of lung-cancer cells, which could be blocked by overexpression of EGFR." (PMID 37240137, 2023). "Besides TNO155, another SHP2i, RMC-4630, is in clinical trials with cobimetinib (an MEKi) in relapsed or refractory solid tumors, and with osimertinib in EGFR+, locally advanced, or metastatic non–small cell lung cancer (ClinicalTrials.gov NCT03989115)." (PMID 36752207, 2023). "Similarly, cryptotanshinone (CTS), a bioactive component of Salvia miltiorrhiza, was shown to sensitize gefitinib‐resistant EGFR‐mutant lung cancer cells by targeting catalase (CAT), heme oxygenase 1 (HMOX1) and stearoyl‐CoA desaturase (SCD)." (PMID 37697969, 2023).
lung cancer (continued). "This implies that exosomes containing EGFR may play a role in promoting immunological tolerance in lung cancer, which has important implications for immunotherapy approaches." (PMID 37641132, 2023). "EGFR-mutant tumors exhibit an increased response rate to tyrosine kinase inhibitors (TKIs) versus EGFR wild-type tumors, while cisplatin-based chemotherapy yields more optimal outcomes in patients with EGFR wild-type lung cancer." (PMID 38094613, 2023). "The results demonstrated that LCOs from patients with EGFR-mutated lung cancer were sensitive to EGFR-TKI but not to ALK inhibitors." (PMID 37508518, 2023). "Q15: Can Osimertinib be considered for EGFR-positive lung cancer patients with brain metastasis but without T790m mutation?" (PMID 37578819, 2023). "For instance, the EM.L2 peptide (QHYNIVNTQSRV) fused with the L2 extracellular domain of human EGFR was expressed in phages, and the phages were tested in a mouse model of lung carcinoma, resulting in the activation of humoral and cellular responses and inhibition of tumor growth." (PMID 37243023, 2023). "Overall, the estimated risk of developing lung cancer among nonsmoking EGFR T790M carriers is 31%, compared with a 0.2% risk in a general population of nonsmokers and an approximately 23% risk in a general population of smokers." (PMID 35320498, 2022). "However, in another study, Braden recorded an up to 55% severe skin ADR rate for lung cancer patients treated with EGFR-TKIs." (PMID 35505288, 2022). "In NSCLC, epidermal growth factor receptor (EGFR) mutations account for 15–40% of cases of non-squamous type and EGFR inhibitors have been used clinically to treat lung cancer caused by EGFR abnormalities." (PMID 36499676, 2022). "Three JAK inhibitors were also among our list of compounds with potential synergy in combination with gefitinib and/or erlotinib, consistent with demonstrations of JAK/STAT signaling as a mechanism of resistance to EGFR targeted therapy in non‐small cell lung cancer." (PMID 35224804, 2022). "One patient with lung cancer had an EGFR (an HSP90 client protein) mutation, while the other did not have any detectable mutation in HSP90 client proteins." (PMID 35932386, 2022). "Notably, DMC–CHC covered with an anti-EGFR antibody layer to assist DMC entrance into the cytoplasmic region exhibits high cytotoxicity against multidrug-resistant lung cancer, particularly NSCLC." (PMID 36358986, 2022). "Overall, only a small proportion of EGFR wild-type lung cancers harbored ROS1 translocation." (PMID 35628598, 2022). "Interestingly, ectopic expression of PKCδ in NSCLC was shown to lead to TKI-resistance in EGFR-mutant lung cancer patients." (PMID 36482371, 2022). "With the aim of mapping proteins related to the non-inflamed TME of EGFR-mutated lung cancer, global proteomics and phosphoproteomics data from cancer tissues were analyzed." (PMID 36482371, 2022). "Known ALK/ROS1 fusions and 5’‐/3’‐end mRNA unbalanced expression were analyzed in 2009 EGFR mutation‐negative non‐small cell lung cancer (NSCLC) samples." (PMID 35322575, 2022). "Furthermore, we found that expression levels of these genes were associated with tumor metastasis; MAP2K1, mTOR, and TEAD1 were significantly overexpressed, while YAP and EGFR were under-expressed in metastasized lung cancer compared to primary tumors." (PMID 35655775, 2022). "In conclusion, in contrast to lung cancer, the study of mutations in the ECD of EGFR, which could activate EGFR, is more valuable than the kinase domain in GBM." (PMID 35814475, 2022).
lung cancer (continued). "On the other hand, the genomic alteration/mutation analysis of the hub-DEGs reflected that most mutation for the EGFR occurred across the four lung cancer studies and was followed by the MYC and CHEK1 genes, since EGFR is a highly mutant/altered gene for lung cancer and NSCLC as well." (PMID 35632527, 2022). "The cell growth process and lung cancer development is influenced by the EGFR gene." (PMID 36016137, 2022). "In addition to its m6A methyltransferase function, METTL3 has also been shown to promote the translation of oncogenes, such as epidermal growth factor receptor (EGFR) in lung cancer, via interaction with ribosomes and the translation initiation complex." (PMID 36733939, 2022). "Suppression of AKT or ERK signals also suppressed the resistance of lung cancer cells to EGFR TKIs." (PMID 35831824, 2022). "Furthermore, a recently proteogenomic study investigating wild-type and mutant-EGFR lung cancer in Taiwan revealed that APOBEC mutagenesis potentially contributed to the early onset of non-smoking lung adenocarcinoma in females." (PMID 36341427, 2022). "XAGE1 (also named GAGED2a) antibodies have been tested in lung cancer patients with or without the EGFR mutation." (PMID 35574342, 2022). "In vitro, we experimentally observed that the combination of an IDH inhibitor and EGFR TKI could better inhibit lung cancer cell proliferation than an EGFR TKI alone." (PMID 35526267, 2022). "EGFR‐mediated signaling transduction is always deregulated in lung cancer." (PMID 35748027, 2022). "The use of selective inhibitors (including the clinically approved anti-diabetic drug epalrestat) to inhibit AKR1B1 can restore the sensitivity of drug-resistant cell lines to EGFR-TKIs and delay drug resistance in mice harboring xenografted tumors derived from lung cancer patients." (PMID 35840984, 2022). "Higher YAP expression was implicated in resistance to a number of cancer drugs including the first- and second-generation EGFR-TKIs, and treatment of lung cancer with growth factor (vascular endothelial growth factor (VEGF) and YAP) inhibitors provided promising results in previous studies." (PMID 35655775, 2022). "Compared to previous studies aimed at studying EGFR-TKI resistance in EGFR-mutant lung cancer, our study evaluated EGFR-TKI resistance from the perspective that the interaction between tumor and immune cells influences the TKI effect, rather than an analysis of tumor cells alone." (PMID 36612121, 2022). "A significant inverse association between higher vegetable consumption and risk of EGFR+ lung cancer was identified, however, this association was not statistically significant among EGFR- lung cancer." (PMID 36530673, 2022). "In addition, curcumin enhances the anticancer activity of gefitinib in vitro and in vivo in lung cancer by inducing EGFR degradation." (PMID 35977996, 2022). "Our observations revealed that radiomic features may help to identify the status of acquired T790M mutation but might have a limited value in predicting the PFS of lung cancer treated with osimertinib after first-line EGFR TKI failure." (PMID 35875167, 2022). "The notch-signalling pathway seems to be one of the EGFR-TKI-tolerance mechanisms in lung cancer." (PMID 35681591, 2022). "WWP1 induces the ubiquitination of EGFR at Lys689, which enhances EGFR recycling in lung cancer." (PMID 35090513, 2022). "Thus, based on the previous and our data, the low TMB can be another mechanism to explain such poor efficacy of immunotherapeutic approaches in EGFR-positive lung cancer." (PMID 36140210, 2022).
lung cancer (continued). "In addition, the expression level of main hub genes (BUB1, CCNA2, CDC20, KIF11) was significantly higher in patients with EGFR TKI-resistant lung cancer tissues (GSE161584) than EGFR TKI-sensitive lung cancer tissues." (PMID 36176446, 2022). "In addition, an in vitro cell model of acquired resistance to osimertinib was established in EGFR mutant lung cancer HCC827 cells (HCC827OR), the IC50 values of which were over 500-fold higher than those of the parental cells." (PMID 36712673, 2022). "Collectively, this study might provide a novel clue for targeted therapy of EGFR specific inhibitor in lung cancer patients." (PMID 35280763, 2022). "An EGFR-mutant lung cancer cell line exposed to EGFR/MEK inhibition in vitro through a combination of osimertinib and trametinib (via a DMSO-containing solution of 100 nM and 30 nM of the former and latter agents respectively) induced a widespread apoptotic response." (PMID 36212398, 2022). "A retrospective study of 308 lung cancer patients who had re-biopsy and 118 patients who had liquid biopsy, found that 134 patients (43.5%) in the re-biopsy group and 49 patients (41.5%) in the liquid biopsy group tested positive for EGFR T790M." (PMID 35209919, 2022). "Additionally, EGFR in plasma exosomes has been suggested to be a possible biomarker for lung cancer diagnosis." (PMID 35158999, 2022). "Specifically, it was not until 2014 that the guidelines from Japanese Lung Cancer Society recommended EGFR-TKI over cytotoxic chemotherapy as first-line therapy for patients with EGFR-mutated advanced NSCLC, in alignment with the guidelines from ESMO and NCCN." (PMID 34652430, 2022). "MiR-1 reduced intratumoral CD8 + T cells in EGFR-TKI resistant lung cancer patients." (PMID 35264191, 2022). "In addition, small/short hairpin RNAs (shRNAs)-induced TET1 knockdown confers resistance to EGFR inhibitors in lung cancer cells." (PMID 35269796, 2022). "Next, we wondered how CAFs strengthened EGFR TKIs resistance in lung cancer." (PMID 35831824, 2022). "One gene that affects lung cancer is the Epidermal Growth Factor Receptor (EGFR)." (PMID 35463723, 2022). "C-MET amplified clones expand in HCC827 lung cancer cells treated by EGFR inhibitors." (PMID 35326664, 2022). "The PIK3CA mutation rate was reported to be 1.8% (14/760) in lung cancer without EGFR-TKI treatment." (PMID 35806042, 2022). "However, a bypass tract capable of activating HIF-1α in EGFR-mutant lung cancer during EGFR suppression was also reported to be related to EGFR-TKI resistance." (PMID 36612121, 2022). "Based on these previous studies, ER-mediated and EGFR-mediated signaling pathways may positively coregulate the cancer-related gene expression during lung cancer progression." (PMID 35589688, 2022). "Furthermore, the curcumin from turmeric, Lupeol (a kind of phytosterol derived from fruits and vegetables), and procyanidins-rich diets have been shown to inhibit EGFR activation and have anti-cancer effects in lung cancer in multiple steps." (PMID 36530673, 2022). "Moreover, p-AKT expression levels are found to be upregulated in EGFR-TKI resistant cell lines compared to their corresponding parental cell lines, and upregulation of p-AKT confers EGFR-TKI resistance in EGFR-mutant lung cancers." (PMID 35301287, 2022). "However, EGFR targeting keep a very important role in lung cancer therapy and several efforts have been conducted in order to maximize efficacy and minimize toxicity of drugs." (PMID 35955669, 2022). "Moreover, the CAFs isolated from patients revealed a significantly increased secretion of Kyn compared to normal fibroblasts HLFs, suggesting the potential role of Kyn metabolism in EGFR TKIs resistance in lung cancer cells." (PMID 35831824, 2022).
lung cancer (continued). "The MassARRAY-based OncoFOCUS panel (v3) was previously adopted in our community pathology lab as a fully validated clinical test of common mutations in BRAF, EGFR, KIT, KRAS, and NRAS genes, which are implicated in various cancers, particularly colon cancer, lung cancer and melanoma." (PMID 35446881, 2022). "Among them, monoclonal antibodies such as Trastuzumab targeting HER2 for the treatment of breast cancer and TK small molecule inhibitors such as Gefitinib and Erlotinib targeting the epidermal growth factor receptor (EGFR) for the treatment of lung cancer have shown their clinical efficacy." (PMID 35628590, 2022). "SHC1 interacts with EGFR to form a protein complex, which may be a new target for lung cancer metastasis." (PMID 35706930, 2022). "For example, an experiment in PC9 (lung cancer cell lines) cells using an EGFR inhibitor resulted in the development of resistance in sensitive cells, which might be due to a transitional epigenetic state." (PMID 35814435, 2022). "We detected 81 different kinds of EGFR genotypes in all 864 lung cancer patients." (PMID 35606799, 2022). "Consequently, we observed that the patterns in resistance-related genes or gene products after short-term exposure to EGFR-TKI varied depending on EGFR-mutant lung cancer cell lines with a different EGFR-TKI resistance mechanism." (PMID 35326664, 2022). "Our findings suggest that dual inhibition of EGFR/HER2 may be a potential treatment option for lung cancer patients harboring oncogenic BCAR4 fusion, even in the absence of EGFR mutations." (PMID 36081848, 2022). "We hypothesized that the others EGFR-positive KRAS mutant cancers were affected similar with EGFR-positive KRAS mutant lung cancers treated with R9VH36 and might reveal the different mechanism between the R9VH36 and EGFR-TKI." (PMID 35578244, 2022). "In addition, depending on EGFR-TKI sensitivity of EGFR-mutant lung cancer cell lines, the expression of cytokines and chemokines was changed differently." (PMID 36612121, 2022). "Its low toxicities, associated with its potential to inhibit several proteins associated with lung cancer (tyrosine kinase, telomerase, NF-κB, ERK1/2, EGFR, STAT proteins, HSP 90, PI3K, Bax, among others), makes them promising prototypes for the development of new anti-lung cancer drugs." (PMID 35056161, 2022). "In all stages, the LCF group with or without EGFR mutations had longer mean survival time than the single lung cancer group." (PMID 36233811, 2022). "In contrast, the lung cancer cells line harbouring an EGFR-mutation, but not a KRAS mutation, H1975 (KRAS-wild type) does not show inhibited colony growth by specific KRAS-inhibition." (PMID 35220407, 2022). "EGFR-targeted fluorescent imaging has been tested in clinical trials for several types of cancer, including head and neck cancer, pancreatic cancer, glioblastoma and glioma, oral cancer, and lung cancer." (PMID 35701793, 2022). "Main prognostic, predictive and therapeutic biomarkers in EGFR-mutant lung cancer." (PMID 36139582, 2022). "RCTs have shown that EGFR-TKIs are breakthrough therapies for advanced lung cancer patients." (PMID 36354696, 2022). "EGFR tyrosine kinase inhibitor (EGFR-TKI) is developing rapidly as a target drug for lung cancer." (PMID 35844793, 2022). "Among the subtypes of lung cancer, adenocarcinoma (a NSCLC) accounts for nearly 50% of cases generally associated with mutations in the kirsten rat sarcoma gene (KRAS), anaplastic lymphoma kinase gene (ALK), or epidermal growth factor receptor (EGFR)." (PMID 35578218, 2022). "However, a non-negligible percentage of cases showed a low response rate to EGFR TKIs due to the intratumoral EGFR heterogeneity in lung cancer." (PMID 35408753, 2022). "We created the ND-conjugated Cet for the detection and tracking of EGFR in lung cancer cells." (PMID 36678740, 2022). "KRAS, ROS1, ALK, and EGFR are the main biomarkers affecting clinical practice of lung cancer." (PMID 36260870, 2022).